ESR1 (estrogen receptor 1)
Diseases named in the same sentence as ESR1 in open-access papers (continued):
Sharing a sentence is not in itself a finding about the gene and the disease.
diabetes (81 papers, 2006 to 2026). "This is the first Palestinian study to conclude that ESR1 PuvII and XbaI variants may contribute to diabetes susceptibility in Palestinian women." (PMID 31293826, 2019). "Thus, the mechanisms underlying the induction of Esr1 mediated by Mafb deletion may provide insights on diabetes therapy." (PMID 35862726, 2022). "Taken together, the influence of the ESR1 gene itself promotes the development of diabetes to a certain extent." (PMID 40508108, 2025). "ESR1 is known to regulate cell proliferation and differentiation, and accumulating evidence also implicates it in the pathogenesis of diabetes." (PMID 40508108, 2025). "In diabetes and obesity-related diseases, ESR1 is also considered to have significant regulatory effects." (PMID 41372957, 2025). "Subsequently, we investigated the possible role of miRNA interference in regulating ESR1 mRNA levels in subcutaneous adipose tissues derived from obese individuals stratified by the presence of diabetes and prediabetes." (PMID 35682668, 2022). "ESR1 was reported to be the key target of AM in the treatment of type 2 diabetes mellitus." (PMID 35267929, 2022). "Interestingly, stratification according to menopausal status revealed that the association between lower ESR1 expression in SAT and prevalence of diabetes was observed in the premenopausal women only." (PMID 35682668, 2022). "Excess adiposity was associated with a significant decrease in the ESR1 and ESR2 mRNA levels in adipose tissue in a depot- and gender-specific manner, and this decrease may predispose patients to the development of diabetes." (PMID 35682668, 2022). "Moreover, we prioritized drug-targets such as melatonin, resveratrol, eugenol, lapatinib, geldanamycin and azathioprine which interacted with ESR1, ERBB2, HSP90AB1 and RAC1, respectively and shown associations in diabetes treatment in experimental models of T1D." (PMID 33841528, 2020). "Among these, seven key targets (JUN, AKT1, ESR1, CASP33, TNF, SRC, and IL6) were found to have the highest network connectivity, indicating their central role in treating diabetes with Chaga." (PMID 40508014, 2025). "The GSE7014 dataset analysis revealed a significant increase in ESR1 expression and a decrease in IL6 expression in diabetes patients, suggesting their potential roles in metabolic dysregulation and inflammation." (PMID 40508014, 2025). "In the GSE7014 dataset, the expression of ESR1 was significantly increased, and the expression of IL6 was significantly reduced in diabetes patients." (PMID 40508014, 2025). "Key targets such as JUN, AKT1, ESR1, CASP3, TNF, SRC, and IL6 were identified as central regulators in diabetes-related pathways, with molecular docking confirming strong binding interactions between Chaga-derived phytochemicals and these targets." (PMID 40508014, 2025). "Specifically, both ESR1 and ESR2 regulate blood glucose levels by altering GLUT4 content in tissues through SLC2A4 gene-expression regulation, thereby improving diabetes conditions." (PMID 40508108, 2025). "Recent studies have shown that some PPARG agonists retain insulin sensitization with few side effects and are widely used in the treatment of type 2 diabetes mellitus; ESR includes ESR1 and ESR2, and most of the effects of oestrogen are mediated by ESR1." (PMID 34164430, 2021).
diabetes (continued). "In order to verify whether ESR1, EP300, NFKB1, and HDAC1 are relevant in ginsenoside treatment of diabetes, Western blot analysis was performed on pancreatic tissue from STZ-induced T1DM mice treated with AD-1." (PMID 40508108, 2025). "Association analyses between ESR1 expression and clinicopathological features showed higher ESR1 expression in EEC patients with no diabetes history." (PMID 40367016, 2025).
Anxiety (74 papers, 2007 to 2025). Intense feelings of nervousness, tension, or panic often arise in response to interpersonal stresses. "ESR1 is also associated with anxiety and depression, which we found to be genetically correlated with EHR-ED (rg = 0.285 ± 0.027)." (PMID 41285899, 2025). "Approximately 90% of patients were male; however, one of the strongest signals was in the intron of the estrogen receptor gene (ESR1), previously implicated in anxiety-like behavior in animal models." (PMID 38328521, 2023). "Increased frequency of rat maternal care (associated with lower anxiety-like behavior) increases Esr1 expression and activity in the medial preoptic area of the hypothalamus in female offspring." (PMID 31704941, 2019). "Taken together, we reasonably speculate that Esr1-positive LSNs are likely implicated in promoting anxiety." (PMID 41208898, 2025). "However, the largest GWAS of anxiety traits to date was able to identify genome-wide significant associations near genes involved with the ERα (ESR1)." (PMID 33494281, 2021). "Therefore, we speculate that either T cell deficiency or type 2-biased T cell responses may enhance ESR1 expression, ESR1 neurogenesis, and/or protection, thereby promoting anxiety." (PMID 41208898, 2025). "In these regions, estrogens highly influence emotional regulation, fear and anxiety processing as well as neuronal excitability via estrogen receptors ESR1, ESR2, and G-protein coupled estrogen receptor (GPER)." (PMID 41323226, 2025). "In our study, 17 core common targets of ACG and anxiety were predicted, of which ESR1, SRC, AKT1, MAPK8, EGFR, and MMP9 belong to the prolactin and estrogen signaling pathways." (PMID 35624976, 2022). "Estrogen receptor 1 (ESR1) is an estrogen receptor subtype, and genetic polymorphisms in ESR1 have been proven to be associated with anxiety in humans." (PMID 35624976, 2022). "Several anxiety-associated genes had direct interactions with striatal development genes, such as PRKCA with ADCY5 and DLX3, and ESR1 with ISL1." (PMID 34526518, 2021). "Notably, an Esr1-positive neuronal subpopulation distributed in the ventral LS exhibited potential responsiveness to changes in peripheral immunity and may participate in anxiety regulation." (PMID 41208898, 2025). "ESR1 is critical for reproduction function, and ESR2 is critically involved in regulating reproductive behaviors, brain development and procession of emotional behavior (anxiety-related behavior e.g.)." (PMID 21303561, 2011).
gastric cancer (71 papers, 2010 to 2025). A primary or metastatic malignant neoplasm involving the stomach. "The ESR1 mutation has been associated with cell proliferation, metastasis, and invasion in gastric cancer." (PMID 38675376, 2024). "ESR1 and androgen receptor (AR) upregulation is associated with a poor prognosis in gastric cancer patients." (PMID 35267457, 2022). "We speculate that ESR1 has diagnostic value in clinicopathological features and prognosis of patients with gastric cancer, and selective targeting of the estrogen receptor may be a new therapeutic tool to eliminate tumor growth and metastasis." (PMID 35686089, 2022). "Melatonin inhibits gastric cancer proliferation by inhibiting estrogen receptor 1 (ESR1) in bisphenol S-induced gastric cancer production." (PMID 40756978, 2025). "NCAPD3 loss can directly inhibit CCND1 and ESR1 expression to downregulate the expression of downstream targets CDK6 and IRS1 and inhibit the proliferation of gastric cancer cells." (PMID 38711992, 2024). "CAF-exosomes promoted cell migration and invasion of gastric cancer through the IL-32/ESR1 pathway." (PMID 39735680, 2025). "Overall, we suggest that LOC441461 modulates gene transcription, inducing the malignancy of gastric cancer by interacting with RELA, IRF1, ESR1, AR, POU5F1, TRIM28, and GATA1." (PMID 35267457, 2022). "The interaction of the transcription factors RELA, IRF1, ESR1, AR, POU5F1, TRIM28, and GATA1 with LOC441461 affected the degree of the malignancy of gastric cancer by modulating gene transcription." (PMID 35267457, 2022). "ESR1, ESR2, and GPER1 mRNA expression data of all gastric carcinoma cell lines were downloaded from the Broad Institute Cancer Cell Line Encyclopedia (CCLE2) and analyzed on Morpheus3." (PMID 33553141, 2020). "In order to further validate whether NCAPD3 directly targets CCND1, ESR1, and MYC to regulate gastric cancer cell proliferation, Co-IP experiments were conducted to examine if NCAPD3 directly interacts with CCND1, ESR1, and MYC." (PMID 38711992, 2024). "In summary, the NCAPD3 protein may target CCND1 or ESR1 to downregulate downstream factors such as CDK6 and IRSI to inhibit gastric cancer cell proliferation." (PMID 38711992, 2024). "Therefore, NCAPD3 knockdown may inhibit CCND1, MYC, and ESR1 activity to downregulate CDK6 and IRS1 expression, thereby inhibiting the proliferation of gastric cancer cells." (PMID 38711992, 2024). "Therefore, NCAPD3 knockdown may inhibit CCND1 and ESR1 expression to downregulate CDK6 and IRSI expression, thereby inhibiting the proliferation of gastric cancer cells." (PMID 38711992, 2024). "Therefore, NCAPD3 knockdown may inhibit CCND1, MYC, and ESR1 expression to downregulate CDK6 and IRSI expression, thereby inhibiting the proliferation of gastric cancer cells." (PMID 38711992, 2024).
thyroid cancer (63 papers, 2011 to 2025). "In literature, it has been shown that the methylation status of markers like RASSF1, DAPK1, and ESR1 has been significantly associated with thyroid cancer subtypes and early detection of thyroid cancer." (PMID 32324757, 2020). "As previously reported, the low ESR1 expression was related to high differentiation, high cell adhesion genes, and low immune response genes expression in adrenocortical and thyroid carcinoma." (PMID 32536040, 2020). "The methylation status of RASSF1, DAPK1 and ESR1 suggests the utility of methylation markers to molecularly differentiate thyroid cancer subtypes for enhanced classification and early detection of thyroid cancer." (PMID 27158284, 2015). "Promoter methylation status of genes with reported associations in thyroid cancer (CASP8, CDKN2A, DAPK1, ESR1, NIS, RASSF1 and TIMP3) were examined in a cohort of follicular thyroid cancers comprising of 26 Hurthle and 27 Classic subtypes utilizing quantitative methylation-specific PCR." (PMID 27158284, 2015). "Protein targets, ESR1 and MAP2K1, act through prolactin, thyroid cancer, endocrine resistance, GnRH secretion, and estrogen signaling pathways." (PMID 38338298, 2024).
breast adenocarcinoma (60 papers, 2005 to 2025). "In a total of 1010 women with resected node-positive early breast adenocarcinoma, the tumoral ESR1/CEP6 gene ratio was suggestive of deletion in 159 (15.7%), gene gain in 551 (54.6%) and amplification in 42 cases (4.2%), with only 30 tumors (3%) harboring five or more ESR1 copies." (PMID 23923010, 2013).
bladder cancer (57 papers, 2007 to 2026). "Several studies have validated the essential role of ESR1 in bladder cancer risk stratification, especially at the tumor grade level, though this cancer is not typically regarded as hormone-related." (PMID 37608369, 2023). "The expression of ESR1 and ESR2 genes (encoding ERα and ERβ, respectively) was thereafter determined in bladder cancer specimens and its prognostic significance was assessed." (PMID 40486871, 2025). "ESR1 has been reported to regulate proliferation in liver cancer, bladder cancer, progenitor Leydig cells, and chondrocytes." (PMID 38711992, 2024). "In a more recent study, the impact of ERα/ESR1 on the initiation of bladder cancer was explored." (PMID 40486871, 2025). "It has been reported that phospho-STAT3 (p-STAT3) induces methylation of estrogen receptor 1 (ESR1) promoter in bladder cancer, and RacGAP1 induces phosphorylation of STAT3, which increases the expression of p-STAT3 and promotes its translocation into the nucleus to play a cancer-promoting role." (PMID 36227136, 2022). "The overexpression and adverse function of RACGAP1 in bladder cancer has undergone confirmation; the underlying mechanism possibly relies on the downregulation of miR-4324 and ESR1, and the upregulation of RACGAP1 and p-STAT3 in the miR-4324-RACGAP1-STAT3-ESR1 feedback loop." (PMID 39858398, 2024). "The results showed that compared with normal tissues, ESR1, PTGS2 and BCL2 in bladder cancer tissues were significantly down-regulated; CASP3, INS, SRC, CDK4, GSK3B and ERBB2 were significantly up-regulated." (PMID 41287122, 2025). "Recent studies have reported the important role of ESR1 in non-small-cell lung cancer (NSCLC) and bladder cancer." (PMID 33865377, 2021). "These hub nodes such as VEGFA, EGFR, ESR1, PLG, and MAPK3 were mainly enriched in pathways like proteoglycans in cancer, bladder cancer, and estrogen-signaling pathway." (PMID 32256653, 2020).
liver cancer (56 papers, 2007 to 2025). An epithelial or non-epithelial malignant neoplasm that arises from the liver. "ESR1 (estrogen receptor 1) exhibits tumor-suppressive behavior in liver cancer, where its downregulation is associated with disease progression." (PMID 41048345, 2025). "Top CGP related to G5 upregulated genes include Alzheimer’s disease dn, liver cancer up, chronic myelogenous leukemia up, ESR1 targets up, and apoptosis by doxorubicin dn." (PMID 41479593, 2025). "In the group of liver cancer patients, the findings indicated that the expression levels of ESR1, SERPINE1, CYP2C9, and CYP3A4 were significantly reduced." (PMID 38905394, 2024). "Liver cancer patients with high expression of ESR1, CYP2C9, and CYP3A4 exhibited a greater overall survival curve compared to those with low expression." (PMID 38905394, 2024). "Based on a PPI network, we ranked each protein by its degree value, and selected the top three core proteins EGFR and ESR1 for potential targets for liver cancer." (PMID 39457402, 2024). "A total of 86 targets of the herbal compound for liver cancer were obtained, mainly five core targets of IL-6, ESR1, JUN, IL1β, and MMP9." (PMID 37680619, 2023). "Nevertheless, ESR1 can be a protective factor in HCC, and the progression of liver cancer is inhibited by ESR1 signaling in vivo." (PMID 37900162, 2023). "In current validated experiments, human liver cancer samples showed upregulated ESR1, EGFR mRNA expressions." (PMID 34592904, 2021). "Liver cancer-resistant Esr1 heterozygous, Esr2 heterozygous, and Esr2 KO females were found to have a uterus weight similar to that seen in intact B6 animals and estrogen-treated ovariectomized B6 mice." (PMID 34068249, 2021). "We identify six genes that are strong candidates for mediating Esr1′s protection against liver cancer." (PMID 34068249, 2021). "In experimental verification, the clinical samples of liver cancer showed elevated ESR1, EGFR mRNA expressions." (PMID 34592904, 2021). "In liver cancer, the ESR1 gene is a low expression gene, while the SPP1 gene is a high expression gene." (PMID 34238253, 2021). "Eight modules are both CNV-TF regulated and CNV-gene enriched, and among these eight CNV-TFs, YY1, MZF1, DAND5, NFYB, ESR1 have been reported in liver cancer development and metastasis." (PMID 24897108, 2014). "However, the GEPIA database showed downregulation of ESR1 in liver cancer, indicating tissue-specific differences in its regulation." (PMID 40508014, 2025). "Furthermore, survival analysis indicated that the expression levels of CYP1A2, ESR1, and AURKA are significantly associated with the prognosis of liver cancer patients, providing potential biomarkers for clinical treatment." (PMID 40864066, 2025). "ESR1 was found to be correlated with survival in liver cancer patients with hepatitis." (PMID 35388301, 2022). "Therefore, the changes in the expression levels of ESR1 and FOBS genes in liver cancer inhibited HALLMARK MYC TARGETS V2 pathway, while HALLMARK HEME METABOLISM, HALLMARK COAGULATION and HALLMARK UV RESPONSE_DN pathways were activated." (PMID 34238253, 2021). "However, in liver cancer tissue, ESR1 and FOBS genes were low in expression, while SPP1 genes were high in expression." (PMID 34238253, 2021). "However, analyses of liver cancer gene expression in clinical samples and of gene function in cultured liver cancer cells suggest Esr1 plays an important role in HCC." (PMID 34068249, 2021). "Moreover, the low ESR1 expression subtypes enriched IDH1 mutations in glioma, liver cancer, and prostate adenocarcinoma." (PMID 32536040, 2020). "It has been found that ESR1 is a direct downstream target of mir-393-3p, and mir-939-3p/ESR1 axis may be a potential new target for the treatment of liver cancer." (PMID 32963562, 2020). "ENO3 and ESR1 protein were downregulated in liver cancer tissues compared with normal tissues." (PMID 31410310, 2019). "However, in liver cancer, both ESR1 and FOBS genes were low expressed." (PMID 34238253, 2021).